ANGPT2 (angiopoietin 2)
Description:
Binds to TEK/TIE2, competing for the ANGPT1 binding site, and modulating ANGPT1 signaling. Can induce tyrosine phosphorylation of TEK/TIE2 in the absence of ANGPT1. In the absence of angiogenic inducers, such as VEGF, ANGPT2-mediated loosening of cell-matrix contacts may induce endothelial cell apoptosis with consequent vascular regression. In concert with VEGF, it may facilitate endothelial cell migration and proliferation, thus serving as a permissive angiogenic signal. Involved in the regulation of lymphangiogenesis.
Synonyms: Ang2; AGPT2; LMPHM10
Tractability: Antibody: an approved drug acts on it; UniProt places it where antibodies can reach, with high confidence; its Gene Ontology location is reachable by antibodies, with high confidence; UniProt predicts a signal peptide or a membrane-spanning region. Other modalities: a drug acting on it is in phase 2 or 3 trials.
Target class: Secreted protein
Gene: Protein-coding gene on chromosome 8 (6,499,632 to 6,563,409, reverse strand). Ensembl gene ENSG00000091879.
Subcellular location: Secreted
Pathways (Reactome):
Hemostasis: Tie2 Signaling
Gene Ontology:
Molecular function: protein binding; receptor ligand activity; receptor tyrosine kinase binding; signaling receptor binding
Biological process: angiogenesis; gene expression; negative regulation of blood vessel endothelial cell migration; negative regulation of positive chemotaxis; positive regulation of coagulation; Tie signaling pathway; glomerulus vasculature development; signal transduction; animal organ regeneration; blood coagulation; cellular response to growth factor stimulus; germ cell development; maternal process involved in female pregnancy; positive regulation of angiogenesis; positive regulation of multicellular organismal process; response to activity; response to glucose; response to hypoxia; response to mechanical stimulus
Cellular component: extracellular region; extracellular matrix
Genetic constraint (gnomAD): Loss-of-function variants: 28 observed, 63.39 expected, observed/expected ratio (o/e) 0.44, 90% interval 0.33 to 0.61. The synonymous counts are far from expectation, so gnomAD's model fits this gene poorly and the ratio says little. Missense variants: 694 observed, 597.82 expected, observed/expected ratio (o/e) 1.16, 90% interval 1.09 to 1.24. Synonymous variants: 274 observed, 210.33 expected, observed/expected ratio (o/e) 1.3, 90% interval 1.18 to 1.44.
Homologues: Orthologues: chimpanzee ANGPT2 (99% identical), macaque ANGPT2 (99% identical), pig ANGPT2 (93% identical), rabbit ANGPT2 (93% identical), dog ANGPT2 (92% identical), rat Angpt2 (87% identical), mouse Angpt2 (85% identical), guinea pig ANGPT2 (85% identical), tropical clawed frog angpt2 (76% identical), zebrafish angpt2a (56% identical). Paralogues in human: ANGPT1 (61% identical), ANGPT4 (45% identical), TNC (27% identical), TNXB (27% identical), ANGPTL2 (26% identical), TNR (26% identical), ANGPTL1 (25% identical), FIBCD1 (25% identical), ANGPTL7 (25% identical), ANGPTL6 (24% identical), FGB (24% identical), FGL2 (24% identical), and 13 more.
Diseases named in the same sentence as ANGPT2 in open-access papers:
ANGPT2 is named in the same sentence as 326 diseases in open-access papers, as found by Europe PMC text mining. Sharing a sentence is not in itself a finding about the gene and the disease. The quoted sentences say what the papers report.
Sepsis (78 papers, 2009 to 2026). Sepsis is defined as life-threatening organ dysfunction caused by a dysregulated host response to infection. "Elevated angiopoietin-2 is associated with diverse inflammatory conditions, including sepsis, a leading global cause of mortality." (PMID 40029709, 2025). "The approach was used to determine the causal effect of the ANG-2 circulating protein levels based on a model of five variants of the ANGPT2 gene in the development of sepsis-induced ARDS in patients of European ancestry." (PMID 37297908, 2023). "Angiopoietin-2 is a vascular growth factor associated with capillary leakage in sepsis, and higher concentrations of this biomarker have been associated with organ dysfunction and worse prognosis." (PMID 37757571, 2023). "The current study aims to investigate the plasma levels of angiopoietin-1 and angiopoietin-2 in patients with severe sepsis and septic shock and their association with the clinical outcome of septic shock in Vietnamese patients." (PMID 36874368, 2022). "Sepsis is known to cause widespread endothelial dysfunction, and angiopoietin-2 has recently gained prominence as an alternative biomarker of sepsis severity." (PMID 35286340, 2022). "In adults with sepsis, ANGPT2 intronic SNPs (rs2442608 and rs2442630) have been associated with increased susceptibility to acute lung injury (ALI) or ARDS across multiple cohorts, one in which plasma ANGPT2 was implicated as a causal intermediate." (PMID 35913450, 2022). "Among four biomarkers of endothelial dysfunction and injury, angiopoietin-2 had the most robust independent association with development of severe AKI in patients with severe sepsis and ARF." (PMID 33541396, 2021). "We chose three markers, soluble tumor necrosis factor receptor-1 (sTNFR1), interleukin-8 (IL8), and angiopoietin-2 (Ang2), which are easily measurable, associate with sepsis outcomes, and represent pathways that are potential targets for sepsis therapy." (PMID 31818332, 2019). "We selected plasma biomarkers, measured at ICU admission, known to be associated with sepsis outcomes, including interleukin (IL)-6, IL-8, granulocyte colony-stimulating factor (G-CSF), angiopoietin-2 (ANG2), and IL-1 receptor antagonist (IL1RA)." (PMID 27431667, 2016). "Attempts to resolve this paradox have gained urgency with markedly elevated ANGPT2 levels being reported in diverse infection- and inflammation-associated conditions, including sepsis and ARDS, anthrax, disseminated coagulopathy, falciparum malaria, and, most recently, severe COVID." (PMID 40029709, 2025). "Furthermore, in subjects of European ancestry with sepsis, ANGPT2 variants predict plasma ANGPT2 levels coupled with ARDS risk." (PMID 38345908, 2024). "Therefore, angiopoietin-1 and angiopoietin-2 have been considered useful biomarkers to improve early diagnosis, risk stratification and prognosis, especially in the early stages of sepsis progression." (PMID 36874368, 2022). "In addition, angiopoietin-2 levels also show a good prognostic performance in severe sepsis and in identifying sepsis patients with higher risk of septic shock development." (PMID 36874368, 2022). "Our present study, in concordance with previous reports, demonstrated plasma angiopoietin-2 levels at enrollment were not only significantly higher in severe sepsis patients with AKI, but also were associated with AKI severity including both KDIGO AKI stage and need for renal replacement therapy." (PMID 33541396, 2021). "First, there might be a subtle developmental effect of complete gene loss that is exacerbated by the stress of sepsis—in the case of Angiopoietin-2, null mice have marked lymphedema from aberrant lymphangiogenesis." (PMID 33618730, 2021).
Sepsis (continued). "Seven biomarkers indicating endothelial dysfunction (mid‐regional proadrenomedullin (MR‐ProADM), syndecan 1, thrombomodulin, angiopoietin 2, endothelial cell‐specific molecule 1, vascular cell adhesion molecule 1 and E‐selectin) had stronger associations with sepsis than infection alone." (PMID 32073224, 2020). "The vascular growth factor Angiopoietin-2 might also be associated with immune regulation, as it has been demonstrated that the ratio of Angiopoietin-2 to Angiopoietin-1 is associated with poor clinical outcome of early sepsis." (PMID 31057415, 2019). "Sepsis-induced cleavage of Angiopoietin-2 converted it from a Tie2 agonist to an antagonist through cathepsin K-mediated proteolysis." (PMID 40029709, 2025). "While released CATK is likely to cleave many soluble proteins in sepsis, our data support that ANGPT2 cleavage is required for the full lethality of sepsis and sufficient to exacerbate septic lethality even when CATK cleavage is inhibited." (PMID 40029709, 2025). "Several additional biomarkers have been proposed for sepsis prognostication, including serum lactate, endothelin-1, angiopoietin-2, and syndecan-1." (PMID 41153844, 2025). "Selective PD-L1 gene deficiency in pmnPD-L1−/− lead to a potentiation of the vascular growth factor Angiopoietin 2 in response to the sequential insult of shock/sepsis." (PMID 41282243, 2025). "Excess ANGPT2 was deleterious in experimental sepsis but actually beneficial in sepsis when its cleavage was prevented." (PMID 40029709, 2025). "The small size of the endogenous ANGPT2 fragment was also suggested by its appearance in the urine of a separate cohort of pediatric patients with sepsis since the human kidney enables filtration of proteins smaller than 60 kDa." (PMID 40029709, 2025). "In sepsis, tumor necrosis factor-α and angiopoietin-2, among others, induce heparanase expression and activation, which causes endothelial dysfunction and organ insult mediated by damage to heparan sulfate, a component of the endothelial glycocalyx." (PMID 39944316, 2025). "Recent studies for endothelial biomarkers in sepsis have found that the activation of the angiopoietin-2/Tie-2 pathway appears to reflect the severity of organ dysfunction in sepsis." (PMID 39090584, 2024). "Angiopoietin-2 (Ang-2) is associated with vascular endothelial injury and permeability in the acute respiratory distress syndrome (ARDS) and sepsis." (PMID 37312169, 2023). "In sepsis, there is an imbalance between the angiopoietin 1 and angiopoietin 2 ratio, with a relative increase in angiopoietin 2 levels." (PMID 38406786, 2023). "The authors found that in the acute phase of sepsis, angiopoietin-1 levels are decreased compared to controls, and angiopoietin-2 levels and ratio are elevated." (PMID 37842022, 2023). "In our study, elevated endothelial function damage markers (angiopoietin-2 and endocan) levels were observed in the plasma of sepsis patients and rats, suggesting the activation and dysfunction of endothelium." (PMID 37559007, 2023). "For example, perturbations of the angiopoietin-2 -Tie 2 axis, a regulator of capillary permeability, have been observed in both sepsis and AMI-CS with elevations of angiopoietin-2 associated with both poor outcome and coronary reperfusion success." (PMID 38012789, 2023). "The levels of both angiopoietin-1 and angiopoietin-2 were significantly increased in sepsis patients compared with control individuals at the time of hospital admission (T0; p = 0.0001)." (PMID 36874368, 2022). "In adults with trauma or sepsis as risk factors for ARDS, the development of ARDS was associated with ANGPT2 and blood type A in White patients, potentially reflecting vascular inflammatory changes." (PMID 35913450, 2022).
Sepsis (continued). "The results showed that angiopoietin-2 levels elevated according to the severity of sepsis progression and were correlated with important clinical parameters such as mean arterial pressure and platelets counts, procalcitonin, lactate levels and SOFA score." (PMID 36874368, 2022). "The current study shows that angiopoietin-2 levels were significantly increased in sepsis patients and those with septic shock." (PMID 36874368, 2022). "Angiopoietin-2 levels accurately discriminated for sepsis with an AUC = 0.97 and septic shock in severe sepsis patients (AUC = 0.778)." (PMID 36874368, 2022). "In conclusion, our data showed that angiopoietin-2 levels were significantly increased while angiopoietin-1 levels were decreased in patients with septic shock compared with those with severe sepsis." (PMID 36874368, 2022). "It should be noted that ABTAA showed greater protection in experimental sepsis, compared to ANGPT2 inhibition alone." (PMID 35740360, 2022). "Angiopoietin-2, which is produced in endothelial cells and pre-stored in the Weibel-Palade bodies, has been correlated with sepsis severity and death and with acute kidney injury and respiratory failure." (PMID 36119052, 2022). "We analyzed the correlation of the levels of angiopoietin-1, angiopoietin-2 and Ang-1/2 ratios with the clinical parameters of sepsis." (PMID 36874368, 2022). "ANGPT2 is increased in several diseases with coagulopathy, including sepsis, and it is plausible that the ANGPT2 inhibition of TM has a role there as well." (PMID 35740360, 2022). "Another study showed that serum angiopoietin-2 levels in patients with systemic inflammatory response, severe infection, sepsis and septic shock were higher than in the control group and were highest in the septic shock group." (PMID 36874368, 2022). "Angiopoietin-2 levels accurately discriminated for sepsis with an AUC = 0.97 and septic shock from severe sepsis patients (AUC = 0.778)." (PMID 36874368, 2022). "Angiopoietin-2 levels were significantly increased in both severe sepsis patients (515.56 pg/ml) and those with septic shock (1096.76 pg/ml) compared with control individuals (105.5 pg/ml) (p < 0.0001)." (PMID 36874368, 2022). "In this regard, in vitro exposition of eGC to endotoxin, TNFα, Angiopoietin-2, or thrombin (all molecules released during sepsis) induced eGC damage." (PMID 36613805, 2022). "Angiopoietin-2 levels were significantly increased in both severe sepsis patients and those with septic shock compared with control individuals (p < 0.0001) and were higher in patients with septic shock compared with severe sepsis patients (p < 0.0001)." (PMID 36874368, 2022). "Taken together, these findings suggest that endothelial dysfunction and injury as measured by circulating angiopoietin-2 levels is more extensive in sepsis patients with severe AKI." (PMID 33541396, 2021). "Patients who died in hospital had higher plasma angiopoietin-2 levels compared to sepsis patients who survived (p < 0.001)." (PMID 33541396, 2021). "Again, angiopoietin 2 is known to stimulate prothrombotic responses through tissue factor and phosphatidylserine exposure in sepsis." (PMID 33430431, 2021). "Plasma angiopoietin-2 levels by quartile were significantly higher in sepsis patients with hepatic, coagulation, and circulatory failure." (PMID 33541396, 2021). "In the present study, we found that several endothelial dysfunction and injury biomarkers, including angiopoietin-2, endocan, sVE-cadherin, and syndecan-1, were higher in sepsis patients who developed severe AKI." (PMID 33541396, 2021). "Previously, this effect of angiopoietin-2 on endothelial hyperpermeability has been studied in the context of sepsis." (PMID 30975180, 2019). "So, a marker for the severity of the state of sepsis would be the rising level of circulating angiopoietin 2, a for-warning of imminent hypovolemia due to interstitial space accumulation of electrolyte/protein-containing fluid with strong osmolar capacity." (PMID 30134544, 2018).
Sepsis (continued). "Whereas Angpt1 can be protective, Angpt2 can worsen outcomes in sepsis, observations that are being used to develop biomarkers in sepsis." (PMID 25959381, 2015). "Most interestingly, the endothelial angiopoietin-2-Tie ligand-receptor system mediates vascular leakage in sepsis, and elevated circulating angiopoietin-2 can be effectively removed by plasma exchange." (PMID 24708653, 2014). "• The consistent association with sepsis, demonstrable dose-response relationship, and temporal progression in patients who develop sepsis make Angiopoietin-2 an attractive potential biomarker in sepsis." (PMID 22248019, 2012). "Angiopoietin-2 (Angpt2), a mediator of endothelial activation and capillary leakage, is known to be up-regulated in sepsis, but its role in ALF has just recently been investigated." (PMID 22973230, 2012). "Serum levels of vascular endothelial growth factor (VEGF), stromal derived factor-1 (SDF-1), and Angiopoietin-2 were higher in sepsis than in healthy controls." (PMID 21396100, 2011). "Previous studies have described linear relationships between plasma ANGPT2 and TNFα concentrations in humans with endotoxemia and sepsis." (PMID 21829546, 2011). "It has also been documented that plasma ANGPT2 levels are elevated in patients with severe sepsis and in children with septic shock, and injection of ANGPT2 protein in vivo elicits significant increases in edema formation in the mouse paw." (PMID 21829546, 2011). "We and others have shown that Angpt2 levels in plasma from critically ill patients with sepsis correlate with the extent of pulmonary vascular leakage in ALI, increase with the severity of AKI, and independently predict mortality in the intensive care unit." (PMID 22040774, 2011). "Serum levels of proangiogenic VEGF, SDF-1, and angiopoietin-2 were higher in sepsis than in healthy controls." (PMID 21396100, 2011). "Notably, ABTAA offered greater protection in sepsis compared with ANGPT2 inhibition alone, underscoring its dual functional advantage." (PMID 40952790, 2025). "We therefore hypothesized that cleavage of ANGPT2 could be a proteolytic switch for converting its function from Tie2 agonist to antagonist in the context of sepsis." (PMID 40029709, 2025). "Regarding indirect ARDS, it has been shown that, in children with sepsis, endothelial activation is accompanied by a relevant increase in some biological factors, including angiopoietin-2, angiopoietin-2/angiopoietin-1 ratio, vascular cell-adhesion molecule, and von Willebrand factor." (PMID 39858517, 2025). "Recombinant ANGPT1 reduces the expression of ANGPT2 induced by sepsis." (PMID 38808888, 2024). "We have previously observed that plasma levels of HS rise in children with sepsis and in preclinical models of sepsis and that HS shedding from the eGC promotes aberrant EC signaling, evidenced by upregulation of the EC-derived cytokine angiopoietin-2 (Angpt-2)." (PMID 39114570, 2024). "Plasma angiopoietin-2 levels may serve as an additional biomarker for severe sepsis and septic shock." (PMID 36874368, 2022). "Angiopoietin-2 levels accurately discriminated for sepsis and septic shock." (PMID 36874368, 2022). "Elevated plasma ANGPT2 is a strong predictor of death in infection-mediated ARDS, independent of the infectious agent, and elevated plasma ANGPT2 is associated with disseminated intravascular coagulation in conjunction with sepsis." (PMID 35740360, 2022). "Angiopoietin-2 levels elevated according to the severity of sepsis progression." (PMID 36874368, 2022). "In sepsis, angiopoietin-2 is upregulated and antagonizes angiopoietin-1." (PMID 36874368, 2022). "Sepsis-related novel biomarkers, including IL-8, IL-6, and angiopoietin-2, were included in the final models, but could also be substituted by other features without significant impact on the performance." (PMID 35453552, 2022). "Moreover, mRNA expression of both Angpt1 and Angpt2 were decreased in the kidney of sepsis patients." (PMID 35634305, 2022).